USP15 (ubiquitin specific peptidase 15)
Diseases named in the same sentence as USP15 in open-access papers (continued):
Sharing a sentence is not in itself a finding about the gene and the disease.
breast cancer (continued). "The role of USP15 in inhibiting breast cancer growth, metastasis, and the attack has been further investigated." (PMID 36213818, 2022). "The expression of phosphorylated USP15 in breast cancer tissues was higher than that in normal tissues." (PMID 36213818, 2022). "The analysis results indicate that the expression level of USP15 is also closely related to the stage of breast cancer and that the expression of USP15 was higher in invasive breast cancer than in other types of breast cancer." (PMID 36213818, 2022). "(p = 6.87e − 04), the phosphorylation expression of USP15 in different stages of breast cancer was also analyzed." (PMID 36213818, 2022). "Analyzing the results, we found that high expression of USP15 was mainly observed in breast cancer patients aged 41-60." (PMID 36213818, 2022). "To further investigate the impact of USP15 on the prognosis of breast cancer patients, we used the TIMER database to examine the effect of USP15 on immune infiltration in different types of breast cancer." (PMID 36213818, 2022). "Xiaet al. analyzed the cell cycle and the apoptosis-related proteins by flow cytometry after silencing USP15 in breast cancer cells, demonstrating that USP15 promotes breast cancer cell proliferation through the cell cycle." (PMID 35203682, 2022). "Using the UALCAN database, we studied the expression of USP15 phosphorylation in breast cancer and normal tissues." (PMID 36213818, 2022). "The results showed that the expression of USP15 in stage 2 and stage 3 breast cancer was higher than in stage 1 breast cancer." (PMID 36213818, 2022). "To further analyze the influence of USP15 expression on breast cancer prognosis, we also performed a statistical analysis on breast cancer staging." (PMID 36213818, 2022). "Meanwhile, USP15 knockdown notably enhanced the antitumor activities of tamoxifen on breast cancer cells." (PMID 33771975, 2021). "By exploring the regulatory mechanisms of ERα at levels of post-translational modifications, we identified the deubiquitinase USP15 as a novel protector for preventing ERα degradation and a critical driver for breast cancer progression." (PMID 33771975, 2021). "In breast cancer cells, USP15 is recruited to TβRI with the assistance of TRAF4, a E3 ubiquitin ligase that also blocks SMURF2 inhibitory effects towards TGF-β pathway via degradation." (PMID 34575114, 2021). "In immortalized HaCaT keratinocytes, USP15 knockdown impairs TGF-β/SMAD-dependent growth arrest but is required for TGF-β-induced cell motility in metastatic MDA-MB-231 breast cancer cells." (PMID 33946990, 2021). "To further identify the role of USP15 in breast cancer, we evaluated its expression using clinical samples from patients with breast cancer." (PMID 33771975, 2021). "It is worth noting that the HER2+/ERα+ breast cancer cells (MDA-MB361) are more sensitivity to USP15 knockdown than HER2+/ERα- breast cancer cells (SK-BR3)." (PMID 33771975, 2021). "TCGA-ACbc cohort indicated that there was deep depletion of USP15 gene in 16.67% of breast cancer patients." (PMID 30874560, 2019). "Based on our studies, we expect that USP15 M861V/D967H contributes to breast cancer etiology, and the patients with these mutants will respond to PARP inhibitor very well." (PMID 30874560, 2019). "For example, in NIH3T3, mouse fibroblast USP15 resides in the cytosol while in MDA-MB-231 human breast cancer cell line, USP15 resides close to the plasma membrane." (PMID 28245560, 2017). "TRAF4 is thus required for efficient TGFβ-induced migration, EMT and breast cancer metastasis in a USP15-regulated fashion." (PMID 25606592, 2014). "Similarly, USP15 inhibits K48-linked ubiquitination of ERα, preventing its degradation, whereas USP15 depletion sensitizes ERα−positive breast cancer cells to tamoxifen." (PMID 40641933, 2025).
breast cancer (continued). "Studies have shown that USP15 knockdown induced downregulation of estrogen receptor alpha protein by promoting its K48-related ubiquitination, which is necessary for proliferation inhibition of breast cancer cells." (PMID 38577597, 2024). "Therefore, we downregulated the expression of USP15 in two breast cancer cell lines, MDA-MB-231 and SUM159, and performed a Western blot analysis of the expression of key proteins in the signaling pathway." (PMID 36213818, 2022). "Moreover, protein immunoblotting assay, cell scratching assay, small compartment invasion assay, 3D stromal gel assay, immunoprecipitation assay, and immunohistochemistry (IHC) were used to USP15 regulatory mechanisms in breast cancer." (PMID 36213818, 2022). "Importantly, we found that there is also a relationship between USP15 expression in breast cancer patients and immunity expression in the data mining process." (PMID 36213818, 2022). "In addition, IHC results further confirmed the high expression of USP15 in breast cancer and its prognostic potential." (PMID 36213818, 2022). "Therefore, it becomes particularly important to study the predictive value and regulatory mechanisms of USP15 in breast cancer to guide breast cancer treatment." (PMID 36213818, 2022). "Through the experimental results, we found that the siUSP15 group can significantly inhibit the invasion and metastasis of breast cancer in the phenotype compared with the NC group, so we can assume that the USP15 plays a role in breast cancer tumor cell invasion and metastasis." (PMID 36213818, 2022). "The selected siUSP15 was verified Based on the experimental results, we found that low expression of USP15 may decrease the ability of breast cancer cells to metastasize and invade." (PMID 36213818, 2022). "Previous reports have proved that USP15 is highly expressed in breast cancer." (PMID 35203682, 2022). ">USP15 is involved in influencing breast cancer metastasis and invasion." (PMID 36213818, 2022). "Our results also offer the opportunity to develop drugs targeting USP15; USP15 may be an attractive predictor of breast cancer prognosis and merits further study in treating breast cancer." (PMID 36213818, 2022). "USP15 expression affects the prognosis of breast cancer patients and is highly expressed in breast cancer cells with strong metastatic and invasive abilities, suggesting that USP15 may affect tumor metastasis and invasion." (PMID 36213818, 2022). "Moreover, the Cancer Genome Atlas showed deletion of USP15 in 16% of breast cancers and 5% of pancreatic cancers." (PMID 33946990, 2021). "In breast cancer, USP15 is found to deubiquitinate and stabilize BMI1 protein at lys-81." (PMID 34179009, 2021). "Investigators also speculated that breast cancer patients with USP15 M861V and D967H mutants are more sensitive to PARPi treatment, suggesting that these two sites contribute to the interaction with BARD1." (PMID 34575114, 2021). "A study found that USP15 affects breast cancer cell sensitivity to PARPi via regulation of HR." (PMID 34575114, 2021). "USP15 stabilizes MDM2, a well-known cancer gene, to regulate cancer-cell survival and mediates antitumor T cell responses, while increased expression of MAD1L1 is associated with poor prognosis in breast cancer." (PMID 31024613, 2019). "However, the predictive value and regulatory mechanism of USP15 in breast cancer are unclear." (PMID 36213818, 2022). "We found that the expression of USP15 in the two cell lines with the strongest metastatic and invasive abilities, MDA-MB-231 and SUM159; this result suggests that USP15 may affect breast cancer prognosis by altering the ability of tumor metastasis and invasion." (PMID 36213818, 2022). "However, USP15 has not been widely studied, so this study proposes that high USP15 expression is significantly associated with poor prognosis in breast cancer patients and reveals a potential regulatory network." (PMID 36213818, 2022).
breast cancer (continued). "The results showed that the expression of USP15 in the triple-negative breast cancer cell lines was significantly higher than that of the MCF-7 ER-positive and PR-positive breast cancer cell lines." (PMID 36213818, 2022). "The authors mainly focused on the roles of several important DUBs in breast cancer, such as USP9X, USP15, and CYLD(Cylindromatosis tumor suppressor protein)." (PMID 34575114, 2021). "USP15 is required for TGFβ-mediated signaling and cell motility in the MDAMB231 metastatic breast cancer cell line." (PMID 25606592, 2014). "Following TGFβ ligand stimulation in breast cancer cells, SMURF2 is degraded in a TRAF4-dependent manner that facilitates recruitment of USP15 to TGFβ receptor I to sustain TGFβ signaling." (PMID 25606592, 2014). "While in tumor cells driven by different oncogenic events, such as MCF7 breast cancer cells, the expression and function regulation of USP15 on TBX3 has not shown such direct correlation." (PMID 38750011, 2024). "Specifically, we demonstrated that USP15 promoted the proliferation of ERα+, but not ERα- breast cancer, in vivo and in vitro." (PMID 33771975, 2021). "Inhibition of USP11, USP4 and USP15 blocks TGFβ-mediated EMT and invasion in breast cancer." (PMID 25606592, 2014).
ovarian carcinoma (14 papers, 2017 to 2025). A malignant neoplasm originating from the surface ovarian epithelium. "Furthermore, USP15 mutations can increase the sensitivity of cancer cells to poly ADP ribose polymerase (PARP) inhibitors that selectively kill breast and ovarian cancer cells with defects in homologous recombination." (PMID 33946990, 2021). "Therefore, USP15 may act as a potential biomarker for predicting the responses of pancreatic, breast, and ovarian cancers to various treatments." (PMID 33946990, 2021). "Oncogenic properties have been reported from ovarian cancer, where USP15 stabilizes HPV16E6, or from divers cancer cell lines where USP15 stabilizes the oncogene REST or MDM2, respectively." (PMID 29299163, 2017).
leukemia (10 papers, 2020 to 2024). A malignant (clonal) hematologic disorder, involving hematopoietic stem cells and characterized by the presence of primitive or atypical myeloid or lymphoid cells in the bone marrow and the blood. "We report that spontaneous genotoxic stress and enhanced sensitivity to clastogenic agents accompanied the decrease in viability of USP15-deficient hematopoietic progenitors and leukemia cells in vitro and mouse primitive hematopoietic progenitors in vivo." (PMID 33378683, 2020). "So when USP15 is reduced in murine precursor cells and leukemia cells, it decreases their ability to proliferate and heightens the level of genotoxicity." (PMID 39048945, 2024). "Van den Berk’s research uncovered that USP15 exhibits elevated levels of expression in human hematopoietic tissues and leukemia." (PMID 39048945, 2024). "When USP15 is reduced in murine precursor cells and leukemia cells, it decreases their ability to proliferate in vitro and heightens the level of genotoxicity." (PMID 39048945, 2024). "Specifically, for onco-hematological diseases, the USP15 gene is usually highly expressed in human hematopoietic tissues and leukemias." (PMID 37373211, 2023). "Given that deletion of USP15 impairs MLL-AF9 AML cell engraftment and delays leukemia development in vivo, we wanted to determine the consequences of USP15 deletion on normal hematopoiesis." (PMID 34465865, 2022). "Recently, a preclinical small-molecule inhibitor of USP15, USP15-Inh, selectively damages leukemia progenitor cells through re-engaging homeostatic redox responses." (PMID 35203682, 2022). "USP15 is highly expressed in human leukemia cells, which interacts with and stabilizes FUS in AML cells." (PMID 34454635, 2021). "To experimentally validate these analyses, we profiled USP15 expression in a panel of 23 leukemia cell lines, including all maturation stages and chemotherapy-resistant CML lines." (PMID 33378683, 2020). "USP15 depletion in murine progenitors and leukemia cells impairs in vitro expansion and increases genotoxic stress." (PMID 33378683, 2020). "Through de novo proteomics, we determined the USP15 interactome in leukemia cells, directly linking USP15 to the regulation of known DDR factors." (PMID 33378683, 2020). "Here, we first analyzed USP15 gene expression in different types of human leukemia using The Cancer Genome Atlas (TCGA) database." (PMID 31952546, 2020). "Consistent with this, USP15 featured the highest of expression in human hematopoietic tissues and related cancers, including leukemia and lymphomas (The Cancer Genome Atlas [TCGA])." (PMID 33378683, 2020). "In leukemia cells, USP15 interacts with and stabilizes FUS (fused in sarcoma), a known DNA repair factor, directly linking USP15 to the DNA damage response (DDR)." (PMID 33378683, 2020). "USP15 is highly expressed in human hematopoietic tissues and leukemias, and it is reported as a critical DUB in protecting genome integrity in hematopoietic stem cells and leukemia cells, playing an important role in the preservation of all major hematopoietic differentiation pathways." (PMID 37373211, 2023). "We reasoned that this observation could either be due to generally high USP15 expression in myeloid tissues compared to other tissue types or due to a unique upregulation of USP15 in leukemia versus normal hematopoietic cells." (PMID 34465865, 2022). "According to these reports, USP15 played indispensable roles in many diseases such as safeguarding genome integrity in leukemia cells, promoting the apoptosis of degenerative nucleus pulposus cells, and enhancing re-epithelialization through deubiquitinating EIF4A1 during cutaneous wound repair." (PMID 33726807, 2021). "USP15 is highly expressed in human hematopoietic tissues and leukemias." (PMID 33378683, 2020).
leukemia (continued). "USP15 inhibition leads to chromosomal aberration, making USP15 a potential target against leukemia." (PMID 32354135, 2020). "We uncovered multiple DUBs as putative regulators of hematopoietic precursors activity and highlighted USP15 as a determinant of hematopoiesis in vivo and its role in preserving genome integrity, with potential implications for combinatorial treatments in leukemia." (PMID 33378683, 2020). "Here, we provide functional ground for investigating the role for USP15 as gatekeeper in leukemia." (PMID 33378683, 2020). "Understanding how USP15 loss precisely impacts HSC and cancer cell maintenance and modulates their damage response may help to identify combinatorial treatment that affect leukemia self-renewal while sparing normal HSC from the side effects of conventional chemotherapy." (PMID 33378683, 2020). "In contrast, the mice engrafted with Usp15−/−;MLL-AF9 cells developed a significantly delayed leukemia, which prolonged the disease for several mice beyond 125 days." (PMID 34465865, 2022). "In keeping with a role of USP15 in DDR, Rad51 protein levels were diminished by USP15 knockdown in MV4-11 and Kasumi-1 leukemia cells." (PMID 33378683, 2020). "Our study underscores the importance of DUBs in preserving normal hematopoiesis and uncovers USP15 as a critical DUB in safeguarding genome integrity in HSCs and leukemia cells." (PMID 33378683, 2020). "In leukemia cells originated by blast crisis such as KBM7 cells, we combined depletion of USP15 by doxycycline (dox)-inducible RNAi and DNA breaks induction by ionizing radiation (IR)." (PMID 33378683, 2020). "One study demonstrated that USP15 could interact with and stabilize a known DNA repair factor called FUS (fused in sarcoma) in hematopoietic stem cells and leukemia cells." (PMID 39522000, 2024). "By 75 days, all mice engrafted with Usp15+/+;MLL-AF9 cells developed leukemia." (PMID 34465865, 2022). "To determine whether the change in USP15 transcripts results in an increase in USP15 protein, we performed immunoblotting for USP15 in CD34+ cells and a panel of leukemia cell lines." (PMID 34465865, 2022). "Mice engrafted with Usp15+/+;MLL-AF9 cells developed leukemia with a median survival of 70 days." (PMID 34465865, 2022). "With the sole exception of the KG1/KG1a cell line, USP15 mRNA was high in all the tested lines and independent of the leukemia stage." (PMID 33378683, 2020).
gastric cancer (8 papers, 2016 to 2025). A primary or metastatic malignant neoplasm involving the stomach. "Ubiquitin-specific protease 15 (USP15) exhibits amplifications in various tumors, including gastric cancer (GC), yet its biological function and mechanisms in GC progression remain elusive." (PMID 39164728, 2024). "In both the TCGA-STAD and PUCH-STAD cohorts, USP15 expression levels were higher in gastric cancer (GC) tissues compared to normal tissues." (PMID 39164728, 2024). "Collectively, knockdown of USP15 in gastric cancer cells could lead to lower level of tumor progression." (PMID 39164728, 2024). "USP15 promotes gastric cancer progression through the Wnt/β-catenin pathway." (PMID 39605891, 2024). "The activities of RBM5 and USP15 were also significantly activated in gastric cancer." (PMID 26897165, 2016). "The silence of USP15 inhibits cell proliferation and invasion in the gastric cancer cell lines BGC-823 and MKN-45 in vivo and in vitro, and USP15 overexpression shows the opposite result." (PMID 35203682, 2022). "In terms of mechanisms, USP15 overexpression promotes the nuclear expression of β-catenin in gastric cancer cells, thereby activating the Wnt/β-caten in signaling pathway to promote the malignant progression of gastric cancer, suggesting that USP15 may be an oncogene of gastric cancer." (PMID 35203682, 2022).